ACKR4 (atypical chemokine receptor 4)
Diseases named in the same sentence as ACKR4 in open-access papers (continued):
Sharing a sentence is not in itself a finding about the gene and the disease.
cancer (13 papers, 2017 to 2025). A tumor composed of atypical neoplastic, often pleomorphic cells that invade other tissues. "CCL3 on CD8+ T cells was also predicted to interact with CCR1 or CCR5 on myeloid cells and CXCL13 on CD8+ T cells was predicted to interact with CXCR5 on B cells or ACKR4 on cancer-associated fibroblasts." (PMID 39478117, 2024). "Some studies have linked ACKR4 to cancer and immune deficiency disease." (PMID 37449198, 2023). "Despite these advances, the role of CCR7/ACKR4 signaling is largely cancer-type dependent, showing either an unfavorable or beneficial role." (PMID 39456552, 2024). "As one of the distinct atypical chemokine receptors, ACKR4 is also involved in the progression of malignant tumors." (PMID 39456552, 2024). "Inflammatory factors CCRL1 (called ACKR4), transcription factor PU.1, and IL-18-driven human helper NK cells participated in the regulation of DC migration, which may contribute to adaptive immune responses that are associated with infection, cancer, or vaccination." (PMID 33681216, 2021). "Taken together, it seems that ACKR4 expressed by cancer cells acts as a negative regulator of tumor progression and plays an important role as a tumor-suppressive factor." (PMID 32456359, 2020). "In this study, and in reports on hepatocellular carcinoma and nasopharyngeal carcinoma, the tumor-restricting effects of ACKR4 were mediated by inhibition of cancer cell proliferation, EMT and/or migration, through abrogation of the relevant chemokine axes." (PMID 32582148, 2020). "There is indeed the “the more advanced/aggressive tumor, the lower ACKR4 expression” trend, but as it concerns normal tissue, the normal-to-expression rate shows apparently less downregulated ACKR4 in more advanced/aggressive cancers." (PMID 33374792, 2020). "ACKR4, which is a receptor for C–C type chemokines, has been shown to bind T cells and dendritic cell-activated chemokines and plays a significant role in controlling the migration of immune and cancer cells." (PMID 34266354, 2021). "Like its ligands, ACKR4 is also involved in the progression of malignant tumors." (PMID 32456359, 2020). "Resembling ACKR1 and many of the functions of ACKR2, ACKR4 demonstrates predominantly tumor-restricting effects, and was positively correlated with patient survival rates in several cancers; at times, ACKR4 expression was inversely correlated with the expression of chemokines in patient materials." (PMID 32582148, 2020). "Since these chemokines are involved in cancer development and metastasis, ACKR4 might be able to inhibit cancer cell proliferation and invasion." (PMID 29497024, 2017). "However, the opposite results were also found in some studies, which indicate that ACKR4 could also have a prometastatic role in cancer development." (PMID 32456359, 2020). "Whereas, CXCR7/ACKR3 has predominantly pro-metastatic roles in cancer, ACKR1 and ACKR4 demonstrate mainly tumor-restricting effects." (PMID 32582148, 2020). "In addition, this study found that DEGs in the three groups were also enriched in cancer and certain disease pathways (TNFSF10, ACKR4, FLT3, SIGLEC1, etc.)." (PMID 40282783, 2025). "Thus, to broaden the scope of atypical activities of chemokine receptors in cancer, a section of the review is dedicated to atypical roles of additional members of the ACKRs sub-group in malignancy: ACKR1, ACKR2, and ACKR4." (PMID 32582148, 2020).
tumor (13 papers, 2020 to 2024). "Studies have shown that a loss of ACKR4 in CRC is tied to reduced immune infiltration in the tumor microenvironment." (PMID 37904433, 2023). "More significantly, compared to stromal cells, the loss of ACKR4 in CRC tumor cells inhibits dendritic cell migration and antigen presentation to the tumor-draining lymph nodes." (PMID 37904433, 2023). "In conclusion, our work indicated that loss of ACKR4 in CRC is associated with poor anti-tumor immune infiltration." (PMID 34638505, 2021). "Higher ACKR4 expression was also associated with more total NK cells, B-cells, and polarized macrophages in the tumor microenvironment." (PMID 34638505, 2021). "Knockdown of ACKR4 in tumor cells impairs the dendritic cell migration from the tumor to the tumor-draining lymph nodes (TdLNs), causing inadequate tumor-specific T-cell expansion and insensitivity to immune checkpoint blockades." (PMID 34638505, 2021). "Histological analysis on human CRC tissues confirmed that ACKR4 high-expressing tumors are associated with a higher number of tumor-infiltrating T-cells." (PMID 34638505, 2021). "Others, in turn, have shown that inhibitory effects of ACKR4 overexpression on tumor growth are associated with downregulating the expression of functional chemokine receptors and thwarting their signaling." (PMID 33374792, 2020). "A key question is whether AKCR4 of tumor cells or ACKR4 of tumor-associated stromal cells affects tumor growth." (PMID 34638505, 2021). "Loss of ACKR4 in CRC is associated with poor immune infiltration in the tumor microenvironment." (PMID 34638505, 2021). "To study whether the tumor growth caused by ACKR4 knockdown was associated with anti-tumor immunity, we analyzed the tumor immune infiltration in the TCGA CRC dataset by the CIBERSORT algorithm." (PMID 34638505, 2021). "Loss of ACKR4 in human CRC was associated with a weak anti-tumor immune response." (PMID 34638505, 2021). "Among them, ACKR4 regulates dendritic cell migration by controlling the ligands and is involved in tumor development in mouse models." (PMID 39290345, 2024). "These chemokines also interact with the atypical chemokine receptors (ACKR2, ACKR3, ACKR4) expressed by both keratinocytes and fibroblasts, provoking excessive Th17 responses and amplifying skin inflammation." (PMID 37308489, 2023). "Our results show that ACKR4 knockdown tumors have fewer CD4+ T-cells but a higher proportion of exhausted CD4+ T-cells in their tumor microenvironment than the control group." (PMID 34638505, 2021). "Although our work has efficiently demonstrated the ACKR4 function in anti-tumor immunity, a few limitations remain." (PMID 34638505, 2021). "Our work demonstrated that in the case of ACKR4 knockdown, tumor-infiltrating DCs are less likely to migrate towards TdLNs, causing a weak tumor-specific T-cell expansion in TdLNs." (PMID 34638505, 2021). "Mechanistically, the knockdown of ACKR4 in tumor cells restricts DC migration from tumor tissue to the tumor draining lymph nodes, thus impairing the tumor-specific T-cell priming and response to ICB." (PMID 34638505, 2021). "We knocked down ACKR4 expression in the host mice by doxycycline treatment before MC38 tumor cell injection." (PMID 34638505, 2021). "Our results indicated that ACKR4 of tumor cells is more competent in regulating tumor growth than the host ACKR4." (PMID 34638505, 2021). "The expression of ACKR2 and ACKR4 in the tumor was, respectively, 3.1-fold and 1.5-fold lower than in patient-matched macroscopically normal tissue." (PMID 33374792, 2020). "The ACKR4 expression ratio (normal-to-tumor) gradually decreased along with increasing lymph node involvement (N0-N1-N2)." (PMID 33374792, 2020).
tumor (continued). "Therefore, a specific monoclonal antibody (mAb) against mouse ACKR4 (mACKR4) is essential to identify and target the ACKR4-expressing cells in the preclinical tumor models." (PMID 39290345, 2024). "Finally, we determined that the CCL21 level in the ACKR4 knockdown tumor tissues was significantly higher than in the wild-type and control groups." (PMID 34638505, 2021). "However, the role of ACKR4 in tumor immunogenicity and overall anti-tumor immunity of CRC has not been determined." (PMID 34638505, 2021). "To see whether the ACKR4 level in the host tissue also affects tumor development, we established a conditional ACKR4 knockdown mouse model." (PMID 34638505, 2021). "Because ACKR4 knockdown reduces the tumor infiltrating T-cells and DC mediated tumor-specific T-cell expansion in the TdLNs, we next evaluated whether ACKR4 knockdown affects the tumor response to immune checkpoint blockade." (PMID 34638505, 2021). "Next, we investigated the immune infiltration in ACKR4 knockdown tumor models." (PMID 34638505, 2021). "Since ACKR4 regulates the CCL21 chemokine gradient, we hypothesized that loss of ACKR4 in tumor tissue would increase the CCL21 levels in the tumor microenvironment." (PMID 34638505, 2021). "Moreover, ACKR4 acts as a negative regulator of tumor progression and modulator of metastatic process." (PMID 32456359, 2020). "All these data suggest ACKR4 might play a role in the activation of tumor-infiltrating pDCs." (PMID 39456552, 2024). "In addition, the knockdown of ACKR4 reduced tumor cells’ sensitivity to ICB." (PMID 36189283, 2022). "Notably, ACKR4 knockdown in MC38 cells significantly accelerated tumor growth." (PMID 34638505, 2021). "Notably, the knockdown of ACKR4 in the tumor cells accelerated tumor growth in vivo." (PMID 34638505, 2021). "Here, we examined the function of ACKR4 in CRC progression and anti-tumor immunity, emphasizing its role in the DC-mediated antigen presentation process and subsequent T-cell activation." (PMID 34638505, 2021). "Taking advantage of the inducible ACKR4 knockdown mice model, we were able to allow the mice to mature with intact ACKR4 expression and selectively downregulate the ACKR4 expression in the host right before and during wild-type MC38 tumor development." (PMID 34638505, 2021). "However, loss of ACKR4 in stromal cells does not significantly affect anti-tumor immunity." (PMID 34638505, 2021). "In contrast, ACKR1, ACKR4 and in many cases also ACKR2 exert anti-tumor functions at conventional migration-related processes as well as at non-conventional aspects." (PMID 32582148, 2020). "Ten chemokine receptors (CXCR1, CXCR2, CXCR4, CXCR6, CCR3, CCR6, ACKR4/CCRL1, CCLR2, CX3CR1, and ACKR1/DARC) were identified as differentially expressed from the DEG analysis between Black, White and Asian patient normal and tumor samples." (PMID 35754051, 2022). "More importantly, loss of ACKR4 in CRC tumor cells, rather than stromal cells, restrains the DC migration and antigen presentation to the tumor-draining lymph nodes (TdLNs)." (PMID 34638505, 2021). "Consequently, the intensity of anti-tumor immunity and response to ICB was significantly restricted by ACKR4 downregulation." (PMID 34638505, 2021). "The ACKR4 level in tumor cells also does not systemically change the frequency and function of immune cells in the tumor-draining lymph nodes." (PMID 34638505, 2021). "The expression ratio (normal-to-tumor) of ACKR2 decreased along with an increasing depth of tumor invasion (T0/1-T2-T3-T4), while that of ACKR4 did not display significant association (ρ = −0.15, p = 0.283)." (PMID 33374792, 2020). "However, ACKR4 expression in the stromal cells did not affect tumor growth." (PMID 34638505, 2021). "However, the knockdown of ACKR4 in host tissue did not significantly alter the tumor development." (PMID 34638505, 2021). "However, the frequencies of tumor-infiltrating CD8+ T-cells and DCs are not influenced by ACKR4 expression." (PMID 34638505, 2021).
tumor (continued). "However, the roles of ACKR4 in CRC development and anti-tumor immunoregulation are not known." (PMID 34638505, 2021).
infection (5 papers, 2019 to 2022). The state of being infected such as from the introduction of a foreign agent such as serum, vaccine, antigenic substance or organism. "These included cytokines and cytokine receptors (Il11, Tnfsf18, and Ackr4), genes involved in infection (Ptgs2 and Heyl), cell adhesion and migration (Spon2 and Mmp10)." (PMID 35293863, 2022).
adenocarcinoma (1 paper, 2020). A common cancer characterized by the presence of malignant glandular cells. "The positive correlation between ACKR4 expression in neoplastic tissue and CCL19 was weak but present in both polyps and adenocarcinomas." (PMID 33374792, 2020).
neurological disorders (1 paper, 2024). "ACKR4 promotes endothelial-to-mesenchymal transition (EndMT) in endothelial cells, which has been reported to be associated with BBB dysfunction in neurological disorders." (PMID 39100897, 2024).
ACKR4 also shares sentences with these, for which no sentence is quoted: pulmonary arterial hypertension (3 papers); liver cancer (2); cervical cancer (1); colon adenoma (1); Colorectal (1); lung carcinoma (1); myocardial infarction (1); pulmonary hypertension (1); tubular adenoma (1); tubulovillous adenoma (1); villous adenoma (1).